MARCKS (myristoylated alanine rich protein kinase C substrate)
Diseases named in the same sentence as MARCKS in open-access papers (continued):
Sharing a sentence is not in itself a finding about the gene and the disease.
malaria (1 paper, 2025). Malaria is a serious and sometimes fatal disease caused by a parasite that commonly infects a certain type of mosquito which feeds on humans. "Compared with those in the control group, the expression levels of key node proteins of Fcγ R-mediated phagocytosis, including SYK, PI3K, PLCγ2, p-MARCKS, CDC42, and RAC, in the spleen samples of the malaria group decreased significantly (P< 0.01 or< 0.05)." (PMID 41425569, 2025). "Compared with those in the malaria group, the expression levels of proteins SYK, PI3K, PLCγ2, and RAC in the spleens of mice in the ZF-CQ group increased significantly (P< 0.01 or< 0.05), and the expression levels of proteins p-MARCKS and CDC42 showed an upward trend." (PMID 41425569, 2025).
mucinous colorectal adenocarcinoma (1 paper, 2020). "Our previous study indicated that SCF/c‐KIT signaling promoted intestinal mucus secretion and development of mucinous colorectal adenocarcinoma by activating PKCδ‐MARCKS, therefore, future studies of this mechanism underlying the reduction in mucus thickness during aging are necessary." (PMID 33040455, 2020).
myeloid malignances (1 paper, 2019). "MARCKS (Myristoylated alanine-rich C kinase substrate) is involved in the tumorigenesis of different types of malignant diseases, but its role in myeloid malignances has not been described." (PMID 31681584, 2019).
myoma (1 paper, 2016). "Mechanistically, it was reported in multiple myoma that MARCKS inhibition causes cell cycle arrest and apoptosis." (PMID 27081703, 2016).
osteosarcoma (1 paper, 2022). A usually aggressive malignant bone-forming mesenchymal neoplasm, predominantly affecting adolescents and young adults. "Furthermore, it has previously been demonstrated that miR-34c suppressed cell growth in vitro and inhibited tumor growth in vivo by targeting MARCKS, thus suggesting that miR-34c was a novel tumor suppressor in osteosarcoma." (PMID 35563590, 2022).
ovary diseases (1 paper, 2019). "Compared to previous literature, just phosphorylations of MARCKS and CAV1 identified in this study were already reported in ovary diseases." (PMID 31442208, 2019).
pulmonary fibrosis (1 paper, 2024). Chronic progressive interstitial lung disorder characterized by the replacement of the lung tissue by connective tissue, leading to progressive dyspnea, respiratory failure, or right heart failure. "In order to explore the TGF-β1 role from plasma or EBC, we have performed an in vitro assay using primary human fibroblasts to analyze a specific marker of pulmonary fibrosis such as phosphorylated myristoylated alanine-rich C-kinase substrate (phosphor-MARCKS)." (PMID 39281687, 2024).
serous ovarian tumors (1 paper, 2017). "Because secretory epithelial cells of the fallopian tubes are the precursors of high-grade serous ovarian tumors, we analyzed MARCKS expression in 27 samples of normal fallopian tube." (PMID 29295532, 2017).
skin cancer (1 paper, 2021). "Interestingly, skin cancer cell line ANST showed overall diverse behavior, regarding downregulation of Cyclin D1, Myc, and SMAD3 as well as upregulation of MARCKS and RICTOR, compared to all other tested cell lines." (PMID 34722291, 2021).
small intestinal adenocarcinoma (1 paper, 2010). "Interestingly MARCKS is inactivated in small intestinal adenocarcinoma and decreased MARCKS levels are observed in transformed cell lines." (PMID 20957176, 2010).
squamous cell carcinoma (1 paper, 2025). A carcinoma arising from squamous epithelial cells. "Squamous cell carcinoma is linked to the expression of MARCKS, CD36, DAB2, ENPEP, and TIMP1." (PMID 40565366, 2025).
Stroke (1 paper, 2015). Sudden impairment of blood flow to a part of the brain due to occlusion or rupture of an artery to the brain. "The slight increase in ventricular volume in MARCKS-null mice (unpublished observations) may be indicative of a potential role for MARCKS on biomechanical properties of stroke in EC cilia." (PMID 26010231, 2015).
viral infection (1 paper, 2008). "Proteins, including cofilin and MARCKS, proliferation marker PCNA, and the energy “linked” protein, pyruvate kinase, were down-regulated after viral infection, whereas calmodulin was up-regulated." (PMID 18575609, 2008).
cancer (50 papers, 2009 to 2025). A tumor composed of atypical neoplastic, often pleomorphic cells that invade other tissues. "Previous studies have implicated MARCKS in aberrant signaling during the development and progression of multiple cancer types, driving cancer metastasis by regulating cancer cell migration and invasion." (PMID 39926275, 2025). "The phosphatidylinositol 3-kinase/AKT pathway, implicated in cancer growth signaling, is related to p-MARCKS and MARCKS." (PMID 38213952, 2023). "Our understanding of the molecular mechanisms underlying the role of MARCKS in promoting cancer metastasis and therapeutic resistance is still incomplete; however, much progress has been made." (PMID 36230850, 2022). "Recently, MARCKS has been studied extensively in several cancers and has been implicated in tumor progression and metastasis." (PMID 36230850, 2022). "MARCKS signaling has been implicated in promoting cancer progression and metastasis in several solid malignancies through the interactions of its highly conserved effector domain with other crucial proteins such as actin, PKC, and AKT." (PMID 36230850, 2022). "Studies have revealed that increased tumor cell expression of MARCKS is associated with poor prognosis in several cancer types." (PMID 36551563, 2022). "Whereas the functional influence of MARCKS on cellular systems extends beyond developmental and maintenance workflow, numerous studies have now indicated that anomalous expression of MARCKS is often associated with several cancers." (PMID 33958003, 2021). "Dysregulation of MARCKS or MARCKSL1 has also been implicated in many different cancers, where they affect tumorigenesis, metastasis and angiogenesis." (PMID 29788979, 2018). "MARCKS, myristoylated alanine-rich C-kinase substrate, has been implicated in aggressiveness of several cancers and MARCKS inhibitors are in development." (PMID 29295532, 2017). "Likewise, another cancer-associated pathway modulated by MARCKS is the Netrin-1 signaling through the Deleted in Colorectal Cancer (DCC) receptor." (PMID 33958003, 2021). "The NF-κB activating protein (NKAP), a protein identified in our analysis to interact with unphosphorylated MARCKS, drew our attention owing to its role in directly activating NF-κB signaling, a smoke-related signaling pathway associated with cancer malignancy 10, 23, 24 (right)." (PMID 33754052, 2021). "Moreover, certain inactivating MARCKS mutations lead to adenocarcinoma, suggesting that MARCKS has a dichotomic role in oncogenesis and tumor suppression depending on the cancer cell type." (PMID 31058089, 2019). "It was suggested that MARCKS stromal overexpression might contribute to cancer-associated fibroblasts activation in EOC and explain their therapeutic resistance and unfavorable prognostic impact." (PMID 29295532, 2017). "Studies in other cancers have associated MARCKS with metastasis." (PMID 29069765, 2017). "Our results suggest that MARCKS overexpression in stromal cells of EOC might contribute to cancer-associated fibroblasts activation and contribute to the poor prognosis of disease." (PMID 29295532, 2017). "We identified many proteins that interact with HER2, including one called MARCKS, which is known to be involved in aggressive types of cancer." (PMID 40940979, 2025). "We next analyzed the Cancer Genome Atlas (TCGA) dataset to investigate broader clinical correlations of MARCKS expression." (PMID 40940979, 2025). "These analyses confirmed membrane localization of MARCKS in carcinoma cells where HER2 was strongly expressed, supporting our in vitro PLA results." (PMID 40940979, 2025). "Among them, MARCKS was ubiquitously overexpressed in all cancer-tissues derived cell subpopulations, and its expression level gradually increased with the differentiation of UTUC tumor cells." (PMID 38903524, 2024). "MARCKS was another interesting protein candidate as it was solely significantly enriched in the cancer group." (PMID 39252972, 2024).
cancer (continued). "BIO-11006, an analog of the MANS peptide containing the active site of MANS (the first 10 amino acids), is superior to MANS as an anti-cancer agent in that it is smaller in size and more soluble, while maintaining identical MARCKS-inhibitory actions." (PMID 36230850, 2022). "The role of MARCKS in tumorigenesis, metastasis, and resistance to anti-cancer therapies of other cancers has also been described." (PMID 35628654, 2022). "Additional studies will be necessary to characterize the roles and mechanisms of MARCKS in therapeutic resistance across cancer types." (PMID 36230850, 2022). "TEVs containing miR-23b derived from mesenchymal bone marrow cancer stem cells (CSC) can induce cancer dormancy via downregulation of the MARCKS gene that mediates breast cancer cells’ differentiation into CSCs through the Wnt-β-catenin pathway." (PMID 36612080, 2022). "Given the growing body of evidence demonstrating that MARCKS plays an important role in cancer stemness, it is possible that MARCKS expression and phosphorylation play an important role in therapeutic resistance." (PMID 36230850, 2022). "More indirectly, our IHC results show the overexpression of MARCKS in cancer cells located in invasive margins in 18 out of 19 tested samples and in tumor emboli." (PMID 36139501, 2022). "Previous studies performed in pancreatic and hematological cancers have also revealed increased MARCKS expression and MARCKS phosphorylation in cancer cells that have developed resistance to drugs such as oxaliplatin and proteasome inhibitors." (PMID 36551563, 2022). "We then discuss the role of MARCKS in cancer metastasis as well as its mechanisms of action in solid tumors." (PMID 36230850, 2022). "MARCKS, a major substrate of PKC, plays a critical role in cancer development and progression and is strongly implicated in cancer metastasis, cancer stemness, and therapeutic resistance." (PMID 36230850, 2022). "This review summarizes recent advances in the understanding of MARCKS on cancer metastasis, stemness, and therapeutic resistance and provides prospects on targeting MARCKS therapeutically." (PMID 36230850, 2022). "Aberrant MARCKS signaling has been observed in the development and progression of multiple cancer types." (PMID 36230850, 2022). "Whereas some hematological malignancies have stressed the importance of the phosphorylated form of MARCKS in cancer development, others specify the involvement of the unphosphorylated protein in governing disease outcomes." (PMID 33958003, 2021). "In this review, we focus on the functional importance of MARCKS in normal and cancer physiology, with an explicit emphasis on hematological cancers." (PMID 33958003, 2021). "To characterize the effects of smoke-induced MARCKS phosphorylation on cell phenotypes relevant to cancer cell aggressiveness, we carried out both scratch/wound healing and Matrigel transwell invasion assays." (PMID 33754052, 2021). "Emerging evidence implies that MARCKS functions as an oncogene playing a critical role in cancer development, progression, and metastasis." (PMID 31058089, 2019). "More broadly, the findings suggest a molecular mechanism for the strong links between phospho-MARCKS and many human cancers." (PMID 29715315, 2018). "The MANS peptide, made up of the myristoylated N-terminal sequence of MARCKS, interferes with mucus hypersecretion, cancer metastasis, and proinflammatory cytokine expression." (PMID 28655899, 2017). "We compared MARCKS expression in normal versus cancer samples, and searched for correlations with clinicopathological features, including overall survival (OS)." (PMID 29295532, 2017). "Several recent data have shown the involvement of MARCKS in cancer aggressiveness, notably metastatic process and therapeutic resistance, and the efficiency of therapeutic inhibition of MARCKS." (PMID 28009981, 2017).
cancer (continued). "MARCKS is significantly overexpressed in human lung SCC relative to adjacent non-cancer tissue and has been identified as a prognostic biomarker in human primary lung SCC." (PMID 27935865, 2017). "MARCKS knockdown reduced cell migration of highly invasive cancer cell lines and suppressed PI3K (phosphatidylinositol 3′-kinase)/AKT phosphorylation and SLUG level." (PMID 28009981, 2017). "In other cancers MARCKS has been described as both tumour suppressive and oncogenic, dependent upon tumour type." (PMID 29069765, 2017). "Many studies have shown the implication of MARCKS in cancer aggressiveness, notably metastatic process and therapeutic resistance." (PMID 29295532, 2017). "We mixed MRC5-CAFs stably transfected with either sh-NC or sh-MARCKS with the SKOV3-Luc cancer cells and coinjected them subcutaneously into NOD/SCID mice." (PMID 27081703, 2016). "MARCKS, a substrate for protein kinase C phosphorylation, displays tumor suppressive roles in multiple cancer types; our study is the first report of MARCKS epigenetic silencing in ACC." (PMID 26963385, 2016). "Based on the novel findings of MARCKS in the nucleus of cancer cells, we examined the literature and MARCKS amino acid sequence to try to identify a potential nuclear localization sequence (NLS)." (PMID 26470026, 2015). "Silencing MARCKS expression in high MARCKS-expressing MDA-MB-231 cells resulted in reducing cancer invasion and migration as compared to control shRNA-transduced cells." (PMID 26015406, 2015). "Recently MARCKS was shown to be a target of miR-21 a micro-RNA that promotes invasion and metastasis in a number of human cancers implicating it as an important tumor suppressor." (PMID 19924305, 2009). "By this method we identified antisense to MARCKS related protein (MRP), whose family member MARCKS is a target of miR-21, a microRNA involved in tumor growth, invasion and metastasis in multiple human cancers." (PMID 19924305, 2009). "Like DMBT1, spatial proteomics implicates MARCKS as being involved in the transition toward cancer." (PMID 39252972, 2024). "In addition, the oncogenic roles of MARCKS in cancer proliferation, metastasis and chemoresistance have also been demonstrated." (PMID 38755678, 2024). "MARCKS has been found to exhibit significant pro-cancer effects in various cancers." (PMID 38287304, 2024). "Therefore, the function of MARCKS and its relationship with other cancer-related genes warrants further investigation." (PMID 38213952, 2023). "In addition to regulating the function of the actin cytoskeleton proteins MARCKS and spectrin in healthy renal epithelial cells, cathepsin B has been studied in cancer and its therapeutic potential has been investigated." (PMID 37239160, 2023). "Finally, we review recent advances in targeting MARCKS as a new therapeutic strategy in cancer management." (PMID 36230850, 2022). "Interestingly, we found an overexpression of MARCKS in cancer cells located in invasive margins in 18 of 19 samples (95%)." (PMID 36139501, 2022). "MARCKS expression and phosphorylation are not universally associated with promoting cancer progression in other solid tumors." (PMID 36230850, 2022). "Moreover, MARCKS contributes to treatment resistance, likely by promoting cancer stem cell renewal as well as immunosuppression." (PMID 36230850, 2022). "MARCKS and MARCKS-like proteins promote cancer stemness and resistance to cancer therapies, demonstrating the potential for MARCKS-targeted therapy as a novel therapeutic strategy to inhibit cancer metastasis and overcome resistance to cancer treatment." (PMID 36230850, 2022). "In this review, we discuss the structure, localization, and function of MARCKS, describe the role and mechanisms of MARCKS in potentiating cancer metastasis and review whether MARCKS contributes to treatment resistance in solid tumors." (PMID 36230850, 2022).